PPP1CA (protein phosphatase 1 catalytic subunit alpha)
Diseases named in the same sentence as PPP1CA in open-access papers (continued):
Sharing a sentence is not in itself a finding about the gene and the disease.
intervertebral disc degeneration (2 papers, 2023 to 2024). "In studies of intervertebral disc degeneration, PPP1CA was shown to mediate nucleus pulposus cell senescence." (PMID 39664902, 2024).
lymph node metastasis (2 papers, 2022 to 2025). "Overexpression of PPP1CA is correlated with poor prognosis, older age, lymph node metastasis, and HER2-positive status." (PMID 40839607, 2025).
neuroblastoma (2 papers, 2011 to 2022). Neuroblastoma (NB) is the most common solid, extracranial childhood tumor. "In neuroblastoma cells, PPP1CA was repressed by miR-125b while its antisense RNA derepressed PPP1CA expression in human neural progenitor cells." (PMID 35877430, 2022). "In mouse N2A neuroblastoma cells, miR-125b significantly downregulated mouse BAK1, PPP1CA, PUMA, and ITCH protein." (PMID 21935352, 2011).
pancreatic cancer (2 papers, 2021). "Data from THPA and patients with pancreatic cancer enrolled in our hospital also confirmed the prognostic value of PPP1CA, PPP1CB, PPP2CA, PPP2CB, PPP3CA, PPP3CB, and PPP6C at the protein level." (PMID 33270085, 2021). "A trend was seen in PPP1CA, PPP1CB, and PPEF1: they were also overexpressed in pancreatic cancer, with fold changes between 1.5 and 2.0." (PMID 33270085, 2021). "In recent years, it has been reported that PPP1CA, PPP1CB, PPP2CA, PPP2CB, and PPP3CA accelerate the progression of pancreatic cancer, while PPP3CB, PPP5C, and PPP6C hinder PAAD progression." (PMID 34125004, 2021). "Results of the present study suggest that PPP1CA, PPP1CB, PPP2CA, PPP2CB, and PPP3CA have deleterious effects but PPP3CB, PPP5C, and PPP6C have beneficial effects on pancreatic cancer." (PMID 33270085, 2021). "Among all the PPPcs, the transcription levels of PPP1CA, PPP1CB, PPP3CA, PPP3CB, and PPP4C were higher in pancreatic cancer than in the normal pancreas." (PMID 33270085, 2021). "In addition, only PPP3CB and PPP6C showed favorable prognostic values with regard to protein level, whereas PPP1CA, PPP1CB, PPP1CC, PPP2CA, PPP2CB, and PPP3CA showed unfavorable prognostic values in pancreatic cancer (P<0.05)." (PMID 33270085, 2021).
cognitive decline (1 paper, 2018). "Protein phosphatase 1 catalytic subunit alpha (PP1A), a hippocampal neuronal protein implicated in neurite growth and the suppression of learning and memory and a potential mediator of cognitive decline during ageing, showed increased relative protein abundance." (PMID 29593495, 2018).
diabetes (1 paper, 2016). "Furthermore, the following genes are involved in diabetes and insulin signaling: MDH2, PPP1CA and HRAS." (PMID 26938218, 2016).
diabetic cardiomyopathy (1 paper, 2022). Diabetic cardiomyopathy is a disorder of the heart muscle in people with diabetes. "We concluded that CaMK2G and PPP1CA are associated with the CaMKII pathway and diabetic cardiomyopathy." (PMID 35767566, 2022).
esophageal cancer (1 paper, 2024). A primary or metastatic malignant neoplasm involving the esophagus. "This relocation of PPP1CA enhances AKT phosphorylation in the cytosol, activates the AKT-mTOR signaling pathway, and contributes to esophageal cancer tumorigenesis." (PMID 38360682, 2024).
leukemia (1 paper, 2025). A malignant (clonal) hematologic disorder, involving hematopoietic stem cells and characterized by the presence of primitive or atypical myeloid or lymphoid cells in the bone marrow and the blood. "Moreover, GSPT1 interacted with ELAVL1 and EIF4B, proteins associated with favorable AML outcomes, while KPNA1 negatively interacted with PPP1CA, a marker of poor prognosis, suggesting its role in modulating negative prognostic pathways in leukemia." (PMID 39940906, 2025). "Furthermore, KPNA1 negatively interacted with PPP1CA, a protein linked to poor prognosis, suggesting a potential role of KPNA1 in modulating negative prognostic pathways in leukemia." (PMID 39940906, 2025).
maxillary sinus squamous cell carcinoma (1 paper, 2024). A squamous cell carcinoma that arises from the mucosal epithelial surface of the maxillary sinus. "In maxillary sinus squamous cell carcinoma, PPP1CA is directly regulated by miR‐874, and silencing PPP1CA inhibits cell proliferation and invasion." (PMID 39550701, 2024).
oral cancer (1 paper, 2018). "In synergy with CCND1, overexpression of the PPP1CA gene, coding for the catalytic subunit of protein phosphatase 1α (PP1α), is responsible for the progression of oral cancer." (PMID 30417146, 2018).
pancreatic adenocarcinoma (1 paper, 2021). "In this work, we found that the mRNA levels of PPP1CA and PPP1CB in pancreatic adenocarcinoma were higher than those in normal tissues." (PMID 33270085, 2021).
triple-negative breast carcinoma (1 paper, 2022). An invasive breast carcinoma which is negative for expression of estrogen receptor (ER), progesterone receptor (PR), and human epidermal growth factor receptor 2 (HER2). "Especially for triple-negative breast cancer (TNBC) patients with high mutation of BRAC1, a promising oncogenic effect may be achieved by inhibiting PPP1CA." (PMID 34964699, 2022).
type 2 diabetes (1 paper, 2022). "The present study obtained CaMK2G and PPP1CA, a gene associated with the CaMKII pathway and type 2 diabetes and acute cardiovascular events, by integrative gene analysis." (PMID 35767566, 2022). "In this study, we obtained CaMK2G and PPP1CA, genes associated with the CaMKII pathway and type 2 diabetes and acute cardiovascular events, by integrative gene analysis and validated their expression in the relevant dataset." (PMID 35767566, 2022). "We also derived that Empagliflozin acts on amino acid TRP-125 of CaMK2G gene and GLN-249 ASP-210 ASP-208 of PPP1CA through CaMKII pathway, thus acting on type 2 diabetes and acute cardiovascular events by molecular docking technique." (PMID 35767566, 2022).
tumor (33 papers, 2007 to 2025). "The catalytic subunit of PP1 is encoded by PPP1CA, PPP1CB, and PPP1CC (protein name PP1γ), and the roles of each subunit in tumor development are inconsistent." (PMID 40626009, 2025). "Next, we established an implanted tumor model using 786-O cells in mice and intratumorally injected cholesterol-modified circPDHK1-siRNA and PPP1CA-siRNA." (PMID 38360682, 2024). "In vivo experiments revealed that PPP1CA expression was induced by abiraterone in resistant tumours, suggesting that PPP1CA is a key factor driving PCa resistance." (PMID 39550701, 2024). "In vivo experiments also revealed that combination therapy significantly inhibited tumour growth and reduced inducible expression of PPP1CA." (PMID 39550701, 2024). "We observed that silencing PPP1CA inhibited circPDHK1-siRNA-induced downregulation of tumor growth in subcutaneously implanted tumors, resulting in decreased tumor volumes and weights." (PMID 38360682, 2024). "Among the 50 most notable DEGs related to ERS displayed in the heatmap, we observed that 26 ERS regulators were dramatically up-regulated in tumor samples, with PPP1CA, CDK5, and TMED9 showing fold changes of 1.25, 1.67, and 1.05, respectively." (PMID 38440732, 2024). "IHC staining and WB results further revealed that abiraterone induced the PPP1CA expression in resistant tumour cells, which was significantly inhibited by nodularin‐R, with the most pronounced inhibitory effects in combination application." (PMID 39550701, 2024). "While the analysis of the methylation of Spinophilin showed increased methylation, the analysis of PPPCs subunits methylation showed a decreased methylation mean, in tumors vs. non-tumor samples, in PPP1CA and PPP1CB, and increased methylation mean in PPP1CC." (PMID 29285244, 2017). "The downregulation of miR-874 was a frequent event in MSSCC, which suggests that miR-874 functions as a tumour suppressive miRNA, directly regulating PPP1CA that has a potential role of an oncogene." (PMID 21847129, 2011). "A previous study suggested that PPP1CA may promote tumor proliferation by disrupting cell cycle regulation." (PMID 40839607, 2025). "Expression analysis also revealed the high PPP1CA expression in tumour tissues of PCa patients." (PMID 39550701, 2024). "IHC staining for Ki-67 and PPP1CA was performed on subcutaneous xenograft tumor tissues." (PMID 38057879, 2023). "PPP1CA promoted tumor cell proliferation and metastasis by activating the MPAK signaling pathway." (PMID 34964699, 2022). "However, the prognosis capability of low Spinophilin combined with low levels of PPP1CA/B or C is clearer in patients with SCC tumors of the lung." (PMID 29285244, 2017). "In addition, PPP1CA can bind to cyclin D1 to phosphorylate RB or can dephosphorylate breast cancer susceptibility protein-1 (BRCA1), all of which induce cell cycle deregulation and promote tumor cell proliferation." (PMID 34964699, 2022). "Interestingly hTERT, MCM5, and PPP1CA were positive in all 7 samples with atypical cells grade 2 or grade 3 that were diagnosed as non-recurrent because no tumors were found at cystoscopy; however, all were diagnosed with a tumor in the follow-up period." (PMID 21106093, 2010). "Overexpression of PEA15, PPP1CA and TUFT1 and a related poorer outcome have also been observed in other tumor entities 35-37." (PMID 34976171, 2022). "Altogether, our results provide evidence for the prevention of tumor angiogenesis through the repression of PEA15, PPP1CA and TUFT1 demonstrating the importance of their downregulation by miR-449a-5p." (PMID 34976171, 2022). "Here we evaluated the diagnostic value of measuring the urinary content of hTERT, MCM5, PPP1CA, and SENP1 mRNAs for detection of tumor recurrence." (PMID 21106093, 2010).
tumor (continued). "To explore the possible role of protein lactylation in driving tumor cell proliferation, we then focused on the Hippo signaling pathway, in which several components or regulatory proteins, such as ACTG1, MOB1A, PPP1CA, YAP, and TEAD1, were found to be lactylated." (PMID 38512451, 2024). "We found significant differences in urinary content of hTERT (p < 0.001), SENP1 (p < 0.001), MCM5 (p < 0.001), and PPP1CA (p < 0.001) transcripts, when comparing urine samples from patients with and without tumor present in the bladder." (PMID 21106093, 2010). "Additionally, proteins involved in the regulation of the cell cycle (e.g., ATM and STAT3), cell proliferation (e.g., LYN and SRRT), metabolism (e.g., GOT2, PPP1CA, and PYGB), and the regulation of Ca2+ flux (e.g., ANXA6 and CALM1) were also found phosphorylated in the tumor cells." (PMID 40129242, 2025). "However, our study found reduced PPP1CA expression in FMC tissues, with no variation across tumor grades or molecular subtypes." (PMID 40839607, 2025).
cancer (22 papers, 2011 to 2025). A tumor composed of atypical neoplastic, often pleomorphic cells that invade other tissues. "PPP1CA is frequently overexpressed in tumors, and some studies have shown that correlations with clinicopathological traits are linked to the emergence of malignant tumors." (PMID 38057879, 2023). "For cancer patients, PPP1CA is often overexpressed, and some studies have linked expression with clinicopathological characteristics." (PMID 38057879, 2023). "A reduction of the levels of PPP1CA mimicked the cancer stem-like cell phenotype of Spinophilin downregulation, suggesting that the mechanism of Spinophilin involves PP1a." (PMID 29285244, 2017). "In conclusion, the reduction of miR-874 and increase of PPP1CA were frequent events in MSSCC cancer cells." (PMID 21847129, 2011). "Although the effects of PPP1CA on the prognosis in PCa patients have not been reported, the risk of its high expression can be verified in other cancer patients." (PMID 39550701, 2024). "In addition, several studies have demonstrated that CDK1, through phosphorylation of BUB1, EZH2 and PPP1CA, alters cell cycle regulation, chromosome segregation, epigenetic control, and DNA replication, leading to cell dysfunction and diseases such as cancer." (PMID 38831458, 2024). "Silencing of the PPP1CA gene significantly inhibited cancer cell proliferation and invasion." (PMID 21847129, 2011). "The function PPP1CA protein and its role in cancer progression, especially for CRC, is unknown." (PMID 38057879, 2023). "However, PPP1CA’s role in cancer development, notably in CRC, is unknown." (PMID 38057879, 2023). "We examined the mRNA and protein expression levels of PPP1CA and PPP4C in clinical samples and showed that both genes were expressed at significantly higher levels in cancer tissues than in paracancerous tissues." (PMID 34964699, 2022). "The expression of NUBP2, PLCB3, PPP1CA, TBCB, and UBE2C were positively correlated with PPP1R14B in the majority of cancer types." (PMID 34858479, 2021). "PPP1CA is reported to be one of three catalytic subunits of protein phosphatase 1 (PP1) and has been shown to be closely related to the development of malignant tumors." (PMID 34858479, 2021). "Three genes, PPP1CA, PAAF1, and TGOLN2 were significantly upregulated in cancer tissues (P=0.0154, P=0.0298, and P=0.0312 respectively)." (PMID 21847129, 2011). "To determine whether MYC and its putative interactor, PP1/PNUTS, are both expressed in cancer, we examine the amplification status of the MYC gene, as well as genes of the PP1/PNUTS holoenzyme (PPP1CA, PPP1CB, PPP1CC, and PPP1R10) in The Cancer Genome Atlas (TCGA) datasets." (PMID 30158517, 2018).
infection (9 papers, 2018 to 2025). The state of being infected such as from the introduction of a foreign agent such as serum, vaccine, antigenic substance or organism. "In agreement with the MS data, infection with H. pylori or 10 min of treatment with cytokines led to the dissociation of PPP1CA, PPP1CB and PPP1CC from TAK1." (PMID 29581850, 2018).
adenocarcinoma (1 paper, 2017). A common cancer characterized by the presence of malignant glandular cells. "We observed that for adenocarcinoma, the patients with low levels of PPP1CA or B have a significantly higher risk of decreased survival than patients with high levels of expression of these genes." (PMID 29285244, 2017). "Finally, we combined low Spinophilin and low PPP1CA/B and C levels and analyzed the predictive capability of survival in patients with adenocarcinoma or SCC tumors." (PMID 29285244, 2017).
PPP1CA also shares sentences with these, for which no sentence is quoted: viral infection (11 papers); colon cancer (2); Hyperkalemia (2); Insulin resistance (2); lung carcinoma (2); melanoma (2); meningioma (2); ZIKV infection (2); autosomal dominant polycystic kidney disease (1); Burkitt lymphoma (1); Chlamydia infection (1); clear cell renal cell carcinoma (1); colon adenocarcinoma (1); encephalitis (1); Glucose intolerance (1); head and neck cancer (1); hemorrhage (1); HIV-1 infection (1); HSV keratitis (1); Hypertension (1); legionellosis (1); liver disease (1); lung adenocarcinoma (1); neurodevelopmental disorder (1); oral squamous cell carcinoma (1); prostate tumours (1); vitiligo (1).